VDR (vitamin D receptor)
Diseases named in the same sentence as VDR in open-access papers (continued):
Sharing a sentence is not in itself a finding about the gene and the disease.
cancer (continued). "We hypothesized that cancer-related abnormalities in VDR, the key factor mediating the function of vitamin D, lead to ineffective activation of the vitamin D signaling pathway, causing vitamin D to be ineffective as a cancer treatment." (PMID 32900990, 2020). "1,25(OH)2D3/VDR signaling pathway restrains cancer stem cell-like properties." (PMID 32820157, 2020). "Through the role of VDR, VD can inhibit proliferation and induce apoptosis of cancer cells through a variety of molecular mechanisms, including via regulation of the activity of genes related to cell proliferation and differentiation, such as p21, p27, c-myc, c-fos, c-jun, laminin and fibronectin." (PMID 33817215, 2020). "1,25-Dihydroxyvitamin D3 (1,25D3), the high affinity ligand for the nuclear VDR, regulates multiple cancer processes (cell cycle, apoptosis, migration, invasion) in vivo and in vitro, however the specific gene targets and mechanisms that mediate these effects are unclear." (PMID 32774770, 2020). "Moreover, VDR-overexpressing cancer stem cells developed fewer and smaller spheroids with higher apoptotic rates mediated by Wnt and β-catenin protein inhibition." (PMID 32560347, 2020). "Skeletal muscle and adipose tissue express the vitamin D receptor and may be a mechanism through which vitamin D supplementation slows cancer progression and reduces cancer death." (PMID 33233566, 2020). "As largely demonstrated, VDR is not only present in cells and tissues involved in calcium regulation, but it is also expressed in malignant cells, by suggesting a pivotal role of vitamin D in cancer growth and progression." (PMID 32560347, 2020). "Liganded VDR signaling has been shown to be attenuated in cancer." (PMID 33291213, 2020). "In addition, calcitriol has been reported to decrease the number of cancer stem cells via a VDR mediated pathway through inhibition of the Wnt pathway." (PMID 32024052, 2020). "Enhanced VDR-mediated transcripts in stromal fibroblasts surrounding cancer cells could predict better survival outcomes." (PMID 32626760, 2020). "Cancer: VDR has been shown to be expressed by cancer cell lines and it is hypothesized to play a role in the pathogenesis and progression of cancer." (PMID 32911795, 2020). "Vitamin D receptor (VDR) is an essential part for the anti‐cancer effect of Calcitriol." (PMID 32285621, 2020). "The main intracellular effect was an enhanced β-catenin transcriptional activity that positively influences c-MYC messenger expression, which is often deregulated in human cancers, and notably involved in cell cycle progression, thus confirming VDR involvement in cancer growth control." (PMID 32560347, 2020). "Taken together, the VDR overexpression both in cancer cells and in the surrounding stromal cells emphasize the great advantage of using vitamin D and its derivatives as anti-cancer agents with a broader therapeutic window against cancer." (PMID 32679655, 2020). "Downstream targets of VDR are genes of mineral metabolism, including calcium and phosphate homeostasis and many other metabolic pathways, including those involved in the immune response and cancer." (PMID 32456160, 2020). "The VDR has a protective role in cancer due to its anti-proliferative and pro-apoptotic actions." (PMID 33634029, 2020). "Beyond its function in the intestinal digestion and fat absorption, this secondary bile acid has demonstrated other biological properties including vitamin D receptor modulation, proteasome regulation and anti-proliferative and pro-apoptotic effects on cancer cells in vitro and in vivo." (PMID 32244717, 2020). "The cumulative OR for the “F” allele of the FokI VDR polymorphism in the tobacco-related cancer group was 1.13 (0.94–1.36 95% CI) and was not statistically significant (p-value = 0.1859)." (PMID 31690771, 2019). "Inducer-stimulation of VDR expression may be useful for cancer therapy in which primary tumor cells exhibit low levels of VDR expression." (PMID 30961641, 2019).
cancer (continued). "Regarding the opposite effect of calcitriol upon the proliferation of cancer and endothelial cells, it is likely that this differential effect might be due to the distinct intracellular localization of the VDR in the two cell lines." (PMID 31698751, 2019). "Hence, the disputed effects of VDR and vitamin D on cancer cells led us to postulate that the antitumour function of vitamin D is not solely borne by VDR and that other molecules are present." (PMID 31819048, 2019). "VDR is linked with FoxO protein and also regulates the sirtuin 1 (Sirt1) class III histone deacetylase (HDAC) and protein phosphatase 1, providing a molecular basis for cancer chemopreventive actions of 1α,25(OH)2D3." (PMID 31653160, 2019). "Considering our findings and those of other studies that support a relevant role of the GR in this type of cancer, it would be useful to revisit the relevance of the expression profile of nuclear receptors (AR, MR, VDR, TDR, etc.), coactivators, corepressors and isoforms." (PMID 30987626, 2019). "Thus, an in-depth dissection of the biological roles of VDR in TME is critical to enable effective VDR-centric cancer treatment." (PMID 30925918, 2019). "Furthermore, in cancerous keratinocytes, 1,25(OH)2D/VDR may alter the expression of genes encoding cytoskeletal proteins, affecting cytoskeletal organization and function resulting in increased cell adhesion and decreased cell motility, even further suppressing cancer growth." (PMID 29951549, 2018). "VDR functionality is necessary for VD mediated anti-cancer activity." (PMID 30060745, 2018). "Thus, although CSCs and their corresponding bulk cancer cells possess comparable VDR expression levels, they exhibit different responses to calcitriol in the VDR signaling activation." (PMID 29581858, 2018). "In support of this hypothesis, our data demonstrated that in terms of induction of VDR downstream gene expression, calcitriol exhibited a more significant effect on ovarian CSCs than bulk cancer cells." (PMID 29581858, 2018). "In vivo and vitro experiments suggested that 1,25(OH)2D3 and its analog EB1089 could suppress the spread of cancer cells through the omentum by binding to VDR present in epithelial cancer and stromal cells." (PMID 30157901, 2018). "Forth, epigenetic silencing of VDR has been reported in cancer." (PMID 29657326, 2018). "Given the CSCs and bulk cancer cells exhibited different sensitivity to calcitriol treatment, we wanted to know whether the VDR signaling in CSCs and bulk cancer cells respond to calcitriol differentially." (PMID 29581858, 2018). "As the alternative vitamin D metabolism pathway via CYP11A1 is just beginning to be understood, its role in cancer and the relative contributions of VDR and ROR are largely unknown." (PMID 29657326, 2018). "1,25(OH)2D/VDR enhances E-cadherin expression and nuclear export of β-catenin and induces the dickkopf 1, an extracellular inhibitor of Wnt signalling, all of which result in the inhibition of cancer growth." (PMID 29951549, 2018). "Furthermore, the mutual heterodimers between RXR and VDR are involved in cancer developments, and activated Ras-Raf-MAPK-ERK can engage in the classical VDR pathway to modulate variously gene expressions." (PMID 29515775, 2018). "In order to perform VDR expression analysis on blood samples collected from a consecutive cohort of 23 metastatic BC patients, we first mimicked the CTCs analysis in blood by mixing cancer cell lines with PBMCs from healthy donors." (PMID 28632174, 2017). "Along this line, the decrease in VitD circulating levels observed in the AH130 hosts as well as in cancer patients could represent a compensatory mechanism aimed at counteracting the increased VDR expression in the skeletal muscle." (PMID 28423519, 2017).
cancer (continued). "We can assume that malignant cells decreased the expression of vitamin D receptor or conversion of 25(OH)D to 1,25(OH)2D to escape the antiproliferative actions of vitamin D, and this may be more prevalent in advanced-stage cancers than earlier stages." (PMID 29113365, 2017). "Finally, a recent study on cancer patients shows a correlation between the presence of specific VDR BsmI and TaqI alleles and CRP plasma levels, one marker of cancer cachexia." (PMID 28423519, 2017). "It was shown that the VDR RNA-level and immunoreactivity is upregulated in cancer cells." (PMID 29113037, 2017). "The biological function of vitamin D, especially its anticancer effects, are largely through activation of VDR, which is required to suppress tumorigenesis and may be a new target for cancer chemoprevention and/or chemotherapy." (PMID 28206978, 2017). "Finally, VDR mRNA expression was also increased in skeletal muscle biopsies of cancer patients with respect to those of control subjects." (PMID 28423519, 2017). "Few studies to date have analysed the associations between VDR or vitamin D pathway genetic variants and cancer outcomes, and no meta-analyses have been published to date." (PMID 28301870, 2017). "Currently, it remains to be seen how the VDR interacts with β-catenin in cancer cells." (PMID 28944088, 2017). "Furthermore, the VDR is expressed in a significant number of tumor tissues, indicating that the receptor influences cancer etiology." (PMID 29113037, 2017). "Other results suggested that vitamin D could have antiproliferative properties for both normal and cancer cells expressing VDR and normal cells, and high doses of vitamin D3 led to G0/G1 cell cycle arrest." (PMID 27058533, 2016). "Since miR-125b is commonly downregulated in cancer cells, it has been proposed that such a decrease in miR-125b may result in the upregulation of VDR and in increasing antitumor effects driven by vitamin D in cancer cell models." (PMID 27293435, 2016). "By binding to the vitamin D receptor (VDR) on the nucleus, it affects target genes involved in intracellular signaling pathways including cell growth, differentiation, adhesion, and apoptosis, making it of interest to study in relation to cancer." (PMID 26867933, 2016). "Similarly, disturbances of the expression of the VDR and enzymes regulating vitamin D activation (CYP27B1) and metabolism (CYP24A1) are linked to the aggressiveness and outcomes of some malignant tumors." (PMID 26501255, 2015). "This means that appropriate levels of VDR could exert positive effects on cancer outcome and could have important implications for designing novel forms of therapy based on treatment with vitamin D or with vitamin D analogs." (PMID 25849303, 2015). "The mechanism of action of the liganded VDR is also dependent on a plethora of enzymes regulating covalent histone modifications, and this epigenetic regulatory system has been found frequently altered in cancer." (PMID 26843863, 2015). "Finally, the VDR seems to modify cancer-related processes by regulating cell proliferation, differentiation, and apoptosis." (PMID 26699871, 2015). "The active metabolite, 1,25(OH)2D binds to the vitamin D receptor, which is expressed in numerous organs such as the intestine, bones, kidneys and in many other tissues and cell types, including immune cells, cardiac myocytes and cancer cells." (PMID 25954901, 2015). "VDR expression was also analyzed in relation to the pathomorphological advancement and we found that the cytoplasmic VDR levels were higher in pTa–T2a tumors compared with samples from more advanced cancers (pT2b–pT4)." (PMID 26501255, 2015). "There is evidence that 1α,25(OH)2D3 protects against tumor formation by several VDR-mediated mechanisms, including regulation of growth arrest, cell differentiation, migration, invasion, and apoptosis, making it a candidate agent for cancer regulation." (PMID 26843863, 2015).
cancer (continued). "The effects of VDR silencing on proliferation were confirmed in several human cancer cell lines." (PMID 25546457, 2014). "However, the roles of VDR and 1,25-(OH)2D3 need further characterization in the context of muscle wasting due to cancer cachexia." (PMID 24782788, 2014). "Based on these considerations, the VDR may be regarded as a mitochondria-targeting tumor facilitator, similar to the role proposed for the leptin receptor, the signaling of which supports cancer cell metabolism by suppressing mitochondrial respiration." (PMID 25546457, 2014). "Such functional interactions between nuclear receptors and TFs, including the antagonistic interaction between RARs and AR and PPARδ, and the agonistic interaction between VDR and AR provide valuable information that can be used to improve cancer prevention and therapy." (PMID 24860512, 2014). "In light of the important biological function of VDR and DBP genetic polymorphisms in cancer development and progression, we hypothesized that genetic variants of the VDR and DBP genes were associated with increased susceptibility to HBV-related HCC." (PMID 25541958, 2014). "Although specific polymorphisms of the VDR gene have been associated with a variety of cancers, VDR mutations have not been reported in human neoplasms." (PMID 24626468, 2014). "This review paper will focus on the evidence of the functions of PPARs and VDR in cancer." (PMID 24202445, 2013). "Vitamin D plays a role in cancer development and acts through the vitamin D receptor (VDR)." (PMID 23554871, 2013). "Considering a number of target genes of VDR and PPARs, these nuclear factors may modulate proliferation and differentiation of normal and cancer cells via various mechanisms." (PMID 24202445, 2013). "Finally, we revise existing data on the relation between vitamin D receptor expression and vitamin D status and the expression of Wnt/β-catenin pathway genes and targets in cancer patients." (PMID 24202444, 2013). "The link between the PPARs and VDR signaling pathways may guide molecular-based treatment strategies and allow the creation of new tools for cancer treatment." (PMID 24202445, 2013). "Higher tumor VDR expression has also been correlated with better prognosis in cancer patients." (PMID 23533810, 2013). "The link between the PPAR and VDR signaling pathways may help guide molecular-based treatment strategies and allow the synthesis of new agents for cancer treatment." (PMID 24202445, 2013). "The role of VDR in cancer has recently attracted much attention." (PMID 23586065, 2013). "With such interactions between ATM and VDR, one would expect that 1,25-VD may affect downstream pathways such as those leading to apoptosis and cell senescence, thereby providing a barrier to cancer development, and protecting genome integrity." (PMID 22498490, 2012). "The FokI polymorphism of VDR/NR1I1 results in distinct translation initiation sites and was shown to have an effect on cell growth inhibition, possibly through estrogen receptor-α protein repression in a cancer cell line." (PMID 22523693, 2012). "Vitamin D Receptor gene (VDR) is involved in the progress of cancers or chronic diseases." (PMID 22206623, 2011). "Patients with carcinomas at early stages that still express VDR could benefit from therapy with 1,25(OH)2D3 compounds that would potentially reduce Wnt/β-catenin oncogenic function." (PMID 21858154, 2011). "Such future advances may provide a rationale for improved prevention and treatment of different cancers, through VDR mediated growth control." (PMID 19737544, 2010). "Our results have shown that the VDR is expressed in carcinomas." (PMID 20831823, 2010). "The vitamin D receptor (VDR) gene is involved in multiple pathways that may be important in the aetiology of cancer." (PMID 22276021, 2009). "Loss of the transcriptional activators MED4 may impair transcription of genes with anti-cancer effect, like the vitamin D receptor." (PMID 19911042, 2009).
cancer (continued). "Thus, targeting the VDR, resulting in overexpression and activation, could be a therapeutic strategy for cancer management." (PMID 41150758, 2025). "The findings also suggest that vitamin D, through its receptor VDR, may be important in impeding disease progression and preventing the development of malignant tumors, as VDR expression was significantly higher in colloid nodules with worse conditions, such as larger nodules and multinodularity." (PMID 40008182, 2025). "In addition, administration of vitamin D may activate the VDR of host normal cells, which can concomitantly inhibit the Wnt/β-catenin signaling in cancer cells with increased sensitivity to chemotherapies." (PMID 40296902, 2025). "In addition, it has been revealed that the VDR could impact on the population of CSCs indicating novel insights on the implications for the application of vitamin D in several cancer therapies." (PMID 40296902, 2025). "In sum, VDR status and signaling may be related to cancer prevention or retrogression." (PMID 38318147, 2024). "The activation of α9nAChR by NNK and nicotine forms a significant feedback loop through PI3K-Akt and MAPK signaling, which could further initiate activator protein 1 (AP1) and vitamin D receptor (VDR) transcription factors stimulation to confer to the cancer development." (PMID 38799236, 2024). "Therefore, we explored genetic alterations of VDR in TCGA pan-cancer atlas." (PMID 38639057, 2024). "However, the underlying mechanisms of the VitD/VDR-mediated effects are not understood in detail and sometimes conflicting reports underline that its role, especially in specific cancer types, remains to be dissected." (PMID 36902107, 2023). "Interestingly, LCA has been shown to interfere with VDR activity, a nuclear receptor that in liver and colon cell systems binds to calcitriol, promoting an anti-inflammatory immune response and enhancing immune surveillance against cancer cells." (PMID 37887360, 2023). "For VDR level is related to many disease formations, monitoring Parkin expression might be an adjunct to the treatment of VDR-related diseases (such as fibrosis and cancer)." (PMID 37056928, 2023). "Additionally, the VDR anti-cancer action is multifaceted and cannot be reduced to a single pathway." (PMID 36364774, 2022). "The absence of vitamin action by VDR mutations also enhances the development of a variety of cancers either at older age or when exposed to other factors that increase cancer risks such as exposure to chemocarcinogenic agents, UVB light, or genes involved in carcinogenesis." (PMID 35334824, 2022). "Taken together, 1α,25(OH)2D3 and VDR-targeted therapy might be a safe and economical approach with pleiotropic effects and broad application scope to promote antitumor responses of patients with cancer." (PMID 35318258, 2022). "Moreover, tissue hypoxia (though not in cancer tissues) caused a drop in VDR, vitamin D binding protein (VDBP), and 25-hydroxylase (CYP2R1) levels while it increased CYP27B1 and CYP24A1 levels." (PMID 35406562, 2022). "Therefore, the nuclear VDR expression of cancer cells may be fundamental for potential 1,25(OH)2D3 anti-cancer effects." (PMID 36362766, 2022). "This can be explained, at least in part, by the fact that VDR is present in most tissues, including the skin, skeletal muscle, endocrine pancreas, immune cells, brain, adipose tissue, breast, vascular tissue, as well as in a number of cancer cells and the placenta." (PMID 33924215, 2021). "Taken into account our results, TNCMC of simple histological seems to represent the subtype in which cancer management using vitamin D may have greater potential, since half of them express VDR, while the vast majority (85.4–100 %) of the other immunophenotypes are VDR-negative." (PMID 34034728, 2021).